IL10 (interleukin 10)
Diseases named in the same sentence as IL10 in open-access papers (continued):
Sharing a sentence is not in itself a finding about the gene and the disease.
metabolic syndrome (122 papers, 2006 to 2026). A cluster of metabolic risk factors for CARDIOVASCULAR DISEASES and TYPE 2 DIABETES MELLITUS. "Previous studies identified significant associations between IL-10 levels and dyslipidemia; IL-10 levels have been inversely correlated with serum levels of total cholesterol, triglycerides, LDL, and VLDL and positively correlated with HDL levels." (PMID 38674931, 2024). "Of note, metabolic syndrome was also associated with lower levels of IL-2 (−2.81 pg/mL), IL-7 (−17.7 pg/mL) and IL-10 (−2.18 pg/mL)." (PMID 39404367, 2024). "This is shown in patients with metabolic syndrome, in which higher IL-10 serum levels are associated with a lower incidence of severe coronary artery disease." (PMID 36297479, 2022). "It has been previously demonstrated that circulating levels of anti-inflammatory cytokine, IL10 are elevated in obese patients while low IL10 levels are associated with the metabolic syndrome." (PMID 35205336, 2022). "Neither was the association with other inflammatory markers statistically significant, although there was a trend towards increased risk of metabolic syndrome for patients with low IL-10 levels." (PMID 35135482, 2022). "High IL-6 combined with low IL-10 levels were associated with risk of metabolic syndrome (OR 3.83, 95%CI 1.07–13.75, p = 0.039)." (PMID 35135482, 2022). "Considerable evidence supports a link between inflammation and the metabolic syndrome; however, the influence of IL-10 deficiency on lipid and glucose homeostasis is incompletely understood." (PMID 36110841, 2022). "Previous study reported that in obese women the prevalence of the metabolic syndrome was associated with low circulating IL-10 levels." (PMID 29895283, 2018). "A high IL-6 combined with a low IL-10 was associated with an increased risk of metabolic syndrome." (PMID 35135482, 2022). "Furthermore, IL-10 is also closely associated with schizophrenia and metabolic syndrome." (PMID 40791199, 2025). "Low IL-10 levels might reinforce the IL-6 mediated risk of developing metabolic syndrome." (PMID 35135482, 2022). "The effects of six weeks of moderate-intensity aerobic exercise supplemented with nano-curcumin on BDNF and inflammatory markers (IL-6 and IL-10) in patients with metabolic syndrome aged 60 to 65 years were also studied by Osali." (PMID 41228407, 2025). "They reported significantly lower TNF-α levels and higher IL-10/TNF-α ratios among participants with metabolic syndrome (p = 0.005), suggesting a pro-inflammatory state." (PMID 40722634, 2025). "Simultaneous use of nano-curcumin and aerobic exercise decreased serum MDA and hs-CRP levels while increasing BDNF, interleukin-10 (IL-10), and total antioxidant capacity in women with metabolic syndrome." (PMID 41228407, 2025). "Conversely, a meta-analysis on aerobic, resistance, and combined training in patients with metabolic syndrome reported increases in IL-6 and IL-10 levels following the combined regimen." (PMID 40219022, 2025). "In one of them, 46 g/day of freeze-dried grape powder, given for 4 weeks, resulted in decreased IL-10 and adiponectin levels in overweight/obese men with metabolic syndrome and dyslipidemia." (PMID 40944222, 2025). "Regarding cardiovascular risk factors (CRF) and IL-10 plasma levels, body mass index (BMI) category (β = 0.59, p = 0.0129) and metabolic syndrome (β = − 1.58, p = 0.0464) influenced IL-10 plasma levels in the CG (adjusted R2: 0.1230, p = 0.0182)." (PMID 38851847, 2024). "This was evidenced by increased CYP1A1, interleukin-10 (IL-10), and IL-22 levels that consequently alleviate metabolic syndrome and inflammation." (PMID 37396381, 2023). "IL‐6 and IL‐10 are markers of both IBD and metabolic syndrome and can cause inflammation in the colon if continuously being produced." (PMID 35189037, 2022). "Kermani and coworkers demonstrated that C. sativus (100 mg/day) reduces VEGF, IL-2, and IL-1β while enhancing IL-10 levels compared to the placebo group in metabolic syndrome patients." (PMID 34956439, 2021).
metabolic syndrome (continued). "When comparing within metabolic syndrome subjects, serum levels of IL-10, IL-1α, and TNF-α revealed a trend towards higher levels in subjects with vitamin D deficiency." (PMID 32178228, 2020). "The gene PBMR1 was described as a repressor of interleukin 10 (IL-10) transcription; an anti-inflammatory cytokine involved in metabolic syndrome." (PMID 29616079, 2018). "Patients with dyslipidemia demonstrated statistically higher expression of the IL10 and IFNA genes, while IFNG, IP10, IRF1, JAK1, and STAT3 were lower in comparison with nondyslipidemic patients." (PMID 28316372, 2017). "Parenteral administration of fish oil in patients with severe acute pancreatitis increases IL-10 and the consumption of fish oil (1.8 g/day, 3 months) by obese patients with dyslipidemia led to higher circulating IL-10 concentrations." (PMID 28287415, 2017). "Literature data have demonstrated that circulating IL10 levels are higher in obese women than in lean women and are lower in women presenting any component of the metabolic syndrome." (PMID 24690978, 2014). "Considering the final sample size of this study and an alpha error of 0.05, the sample power (1−β) was 1.00 for NO, 0.96 for IL-10/NO ratio and 0.71 for metabolic syndrome z score." (PMID 25379699, 2014). "Plasma IL-10 (p < 0.05) and adiponectin concentrations (p < 0.05) followed opposite outcomes based on dyslipidemia category." (PMID 23222963, 2012). "MyD88 inhibition or IL-10 elevation in adipose tissue may represent a novel strategy for metabolic syndrome." (PMID 41898743, 2026). "In this regard, an alteration of Raw, marked by an increase in pro-inflammatory parameters, such as leptin, IL-1 beta, IL-8, and TNF-alpha, and a decrease in anti-inflammatory parameters, such as adiponectin and IL-10, has been seen in older adults with metabolic syndrome." (PMID 40095561, 2025). "Like IL-10’s implications in metabolic syndrome, IL-1β plays a role in this intricate scenario." (PMID 38674931, 2024). "The statistically significant difference in IL-10 levels between the groups with and without metabolic syndrome suggests a possible association with this condition." (PMID 38674931, 2024). "However, only the IL10 -3575T>A (rs1800890) SNP genotypes correlated significantly with metabolic syndrome, with the AA genotype having a higher frequency of participants with metabolic syndrome." (PMID 38674931, 2024). "However, the clinical relevance of these findings must be carefully considered, as several variables in addition to IL-10 influence metabolic syndrome." (PMID 38674931, 2024). "On the other hand, an impaired IL-10 response on a proinflammatory stimulus is related to the presence of metabolic syndrome and T2D in old individuals, and B cells from patients with T2D show diminished IL-10 secretion on stimulation of its toll-like receptors." (PMID 36262060, 2023). "A recent study has shown that propionate could attenuate dyslipidemia by increasing the regulatory T-cell number and interleukin 10 level of the intestinal microenvironment." (PMID 36625637, 2023). "In addition, we provide evidence supporting the role of IL-10 as a counteracting response to IL-6 mediated inflammation, thereby preventing development of metabolic syndrome." (PMID 35135482, 2022). "It has been reported that MSC-EVs isolated from adipose tissues can improve the structure and function of the kidney and reduce kidney damage and dysfunction by upregulating interleukin 10 (IL-10) expression in a new porcine model of metabolic syndrome (METS) and renal artery stenosis (RAS)." (PMID 35910853, 2022). "High IL-6 combined with low IL-10 levels were associated with risk of metabolic syndrome (OR 3.83, 95%CI 1.07–13.75), however not statistically significantly after adjustment." (PMID 35135482, 2022).
metabolic syndrome (continued). "Dyslipidemia regulates both innate and adaptive immune reaction by releasing pro-inflammatory cytokines, which contribute to the activation and polarization of T-helper 2 (Th-2) and Th17 as well as inhibiting interleukin-10 (IL-10) cytokine production." (PMID 35546679, 2022). "In an Italian study, IL-10 levels were higher in obese women than in non-obese women, but were in both groups negatively associated with metabolic syndrome." (PMID 35135482, 2022). "IL-10 substitution might pose a viable treatment strategy for atrial dysfunction (arrhythmias, contractile dysfunction) in the setting of metabolic syndrome-related HFpEF and its efficacy should be further evaluated in preclinical trials." (PMID 32937823, 2020). "In situations of inflammation, common in metabolic syndrome, a variety of mediators (including tumor necrosis factor-α, interleukin 6, and interleukin 10) could have an impact on NF-κB pathway." (PMID 30945110, 2019). "Eirin A and colleagues used a porcine model of metabolic syndrome and renal artery stenosis and confirmed that extracellular vesicles derived from mesenchymal stem cells mitigated renal inflammation, which was mediated by IL-10." (PMID 29050313, 2017). "Interestingly, overexpression of resistin led to an inhibition of the production of IL-10, which limits inflammatory responses and promotes insulin sensitivity and is also down-regulated in metabolic syndrome." (PMID 16854242, 2006). "Therefore, our results of increased levels of Tr1 cells and CD4+IL-10+ lymphocytes in T2DM are in agreement with previous reports regarding increased serum levels of IL-10 in patients with this condition as well as in prediabetic individuals and patients with metabolic syndrome." (PMID 38183564, 2024). "Interestingly, a combination of high IL-6 and low IL-10 levels was associated with an increased risk of metabolic syndrome, although not statistically significantly after adjusting for confounders." (PMID 35135482, 2022). "In patients with metabolic syndrome, the results presented by Alizaei Yousefabadi (2021) demonstrate a significant reduction in TNF-α, CRP, and IL-8 but an increase in IL-10 after a 12-week follow-up period." (PMID 40559680, 2025). "Ad-MSC expression of miR-155 appears blunted in visceral obesity, which correlates with Ad-MSC IGF-1 hypersecretion and IL-10 hyposecretion, systemic microinflammation, and HDL dyslipidemia." (PMID 38928349, 2024). "In the ACS group, only dyslipidemia (β = 1.79, p = 0.0364) and HBP (β = − 2.37, p = 0.0183) shown an effect in the variation of IL-10 levels (adjusted R2: 0.046, p = 0.0226)." (PMID 38851847, 2024). "The concentrations of early metabolic syndrome biomarkers [adiponectin, leptin, TNF-α, IL-1, IL-6, IL-10, endothelin-1, apolipoprotein B, and lipoprotein (a)] were measured and a cardiopulmonary exercise test (CPET) was performed." (PMID 38254811, 2024). "It has been demonstrated that PD patients with dyslipidemia had significantly higher levels of IL-10, TNF-α, and MCP-1 in PDE compared to dyslipidemia-free patients." (PMID 39457689, 2024). "In this in vivo study, HD of EBN continues to lead in upregulating levels of PGC-1α, IL-10, SOD, and downregulation of TNF-α; which will reduce the complications of metabolic syndrome." (PMID 37764670, 2023). "IL10 and SOD2 were lowly expressed in metabolic syndrome, and their expression levels were up-regulated after exercise (P < 0.05)." (PMID 37053002, 2023). "In a porcine model of metabolic syndrome (MetS), the systemic administration of ADMSC-EVs restored kidney function and reduced tubulointerstitial fibrosis by IL-10-dependent immunoregulation." (PMID 36341339, 2022). "Recently, in a model of metabolic syndrome, a high-fat diet, supplemented with 12% (w/w) of freeze-dried T. lutea, significantly reduced plasma TNF-α levels and increased IL-10 in abdominal adipose tissue." (PMID 34207952, 2021).
metabolic syndrome (continued). "The aim of this research was to investigate the effect of 6-week aerobic exercise with moderate intensity and consumption of nano-curcumin on IL-6, IL-10 and BDNF in 60–65 year females with metabolic syndrome (MS)." (PMID 32256716, 2020). "In contrast to the IL10 and IFNA genes, the present study demonstrates lower expression of IFNG in the groups composed by patients with dyslipidemia (G1, G2, and G3)." (PMID 28316372, 2017). "In summary, ten weeks of CT reduced blood markers of inflammation such as NO, IL-10 and OPG, blood pressure and metabolic syndrome Z scores in women with MetS." (PMID 25379699, 2014). "Moreover, supplementation with DHA extracts from the haptohyte Tisochrysis lutea in an animal model of metabolic syndrome lowered the plasma levels of the pro-inflammatory marker TNF-α, while increasing the production of the anti-inflammatory cytokine IL-10." (PMID 39997210, 2025). "There have not been many studies comparing the levels of IL-10 between sexes; we found only one study that suggested a close association between low levels of IL10 with a metabolic syndrome in a group of women." (PMID 36213511, 2022). "For example, lower levels of anti-inflammatory cytokines, including IL-4, IL-13, and IL-10, have been found in obese subjects with metabolic syndrome compared to those without metabolic syndrome." (PMID 36313072, 2022). "In addition, the results of the present study suggested that nano-curcumin supplementation significantly increases serum concentrations of BDNF, IL-10, and TAC in subjects with metabolic syndrome." (PMID 32256716, 2020). "Obese humans with metabolic syndrome had lower levels of IL-10 compared to subjects without metabolic syndrome." (PMID 33178196, 2020). "In addition, the results of the present study suggested that nano-curcumin supplementation significantly increases serum concentrations of BDNF, IL-10, and total antioxidant capacity (TAC) in subjects with metabolic syndrome." (PMID 32256716, 2020). "In conclusion, we found that participants without dyslipidemia showed a more favorable response to GRAPE consumption by increasing plasma IL-10 and adiponectin levels, compared to placebo." (PMID 23222963, 2012). "In this study, we have demonstrated that grape consumption increases IL-10 and adiponectin, two anti-inflammatory cytokines only in those subjects who do not present dyslipidemia (elevated TG and low HDL-C)." (PMID 23222963, 2012). "Furthermore, this nano-curcumin increased brain-derived neurotrophic factor and IL-10 levels, as well as antioxidant capacity, in the blood from subjects with metabolic syndrome." (PMID 36678282, 2023). "In a novel porcine model of coexisting metabolic syndrome (MetS) and renal artery stenosis (RAS), MSC-EVs isolated from adipose tissue were capable of improving renal structuring and function, and reducing renal injury and dysfunction by up-regulating the level of IL-10 expression." (PMID 34646275, 2021). "Additionally, the anti-inflammatory cytokine IL-10 is capable of inhibiting synthesis of pro-inflammatory cytokines, such as IFN-γ, IL-2, IL-3, and TNFα released by macrophages and Th1 cells, while low levels of IL-10 have been reported in patients with T2DM and metabolic syndrome." (PMID 33802371, 2021). "In addition, plasma IL-10 levels were higher in the GRAPE period compared with placebo in participants without dyslipidemia (p < 0.005)." (PMID 23222963, 2012). "Thus, we observed that only participants without dyslipidemia (possibly with normal IL-10 production capacity) responded favorably to GRAPE consumption by increasing their plasma IL-10 levels." (PMID 23222963, 2012). "Expression of IL-10 appears to be complex, such that individuals exhibiting symptoms of metabolic syndrome, whether obese or nonobese, exhibit lower levels of IL-10 compared to their obese and nonobese counterparts, possibly due to the distribution of M1/M2 macrophages." (PMID 23844276, 2013).
metabolic syndrome (continued). "Statistically significant differences were observed between the groups with and without metabolic syndrome (MetS), even as participants with MetS had reduced serum cytokine levels (p < 0.001), regarding the research participants’ clinical status and serum IL-10 concentrations." (PMID 38674931, 2024). "Changes in plasma adiponectin (p < 0.05), interleukin (IL)-10 (p < 0.005) and in mRNA expression of the inducible isoform of nitric oxide synthase (iNOS) (p < 0.25) were increased in the GRAPE compared to the placebo period only in those individuals without dyslipidemia." (PMID 23222963, 2012).